NDUFAF8 (NADH:ubiquinone oxidoreductase complex assembly factor 8)
Description:
Involved in the assembly of mitochondrial NADH:ubiquinone oxidoreductase complex (complex I, MT-ND1). Required to stabilize NDUFAF5.
Synonyms: C17orf89; MC1DN34
Tractability: PROTAC: ubiquitination databases record sites on it.
Gene: Protein-coding gene on chromosome 17 (81,239,305 to 81,241,310, forward strand). Ensembl gene ENSG00000224877.
Subcellular location: Mitochondrion
Subcellular location (Human Protein Atlas): Mitochondria
Pathways (Reactome):
Metabolism: Complex I biogenesis
Gene Ontology:
Molecular function: protein binding
Biological process: mitochondrial respiratory chain complex I assembly
Cellular component: mitochondrial matrix; mitochondrion
Genetic constraint (gnomAD): Loss-of-function variants: 10 observed, 8.46 expected, observed/expected ratio (o/e) 1.18, 90% interval 0.72 to 1.83. That is too few expected variants to judge how well the gene tolerates losing a copy. Missense variants: 114 observed, 84 expected, observed/expected ratio (o/e) 1.36, 90% interval 1.16 to 1.59. Synonymous variants: 63 observed, 43.62 expected, observed/expected ratio (o/e) 1.44, 90% interval 1.18 to 1.77.
Gene-disease validity (ClinGen):
ClinGen rates the evidence that NDUFAF8 causes each of these diseases.
Leigh syndrome (autosomal recessive): Moderate. A progressive neurological disease defined by specific neuropathological features associating brainstem and basal ganglia lesions.
mitochondrial disease (autosomal recessive): Moderate.
Homologues: Orthologues: chimpanzee NDUFAF8 (99% identical), macaque NDUFAF8 (95% identical), dog NDUFAF8 (88% identical), mouse Ndufaf8 (86% identical), pig NDUFAF8 (84% identical), guinea pig NDUFAF8 (81% identical), rat Ndufaf8 (81% identical), zebrafish ndufaf8 (49% identical).
Diseases named in the same sentence as NDUFAF8 in open-access papers:
NDUFAF8 is named in the same sentence as 8 diseases in open-access papers, as found by Europe PMC text mining. Sharing a sentence is not in itself a finding about the gene and the disease.
NDUFAF8 shares sentences with these, for which no sentence is quoted: breast carcinoma (1 paper); bronchial hyperreactivity (1); cancer (1); Leigh syndrome (1); neurological disease (1); pancreatic cancer (1); Salmonella Infections (1); tumor (1).